JAG1 (jagged canonical Notch ligand 1)
Diseases named in the same sentence as JAG1 in open-access papers (continued):
Sharing a sentence is not in itself a finding about the gene and the disease.
diabetes (11 papers, 2012 to 2025). "The gene expression levels of JAG1 are closely associated with human diabetes, increasing the risk of developing the disease." (PMID 40026415, 2025). "Furthermore, cytokines play a crucial role in inflammatory diseases such as diabetes and are implicated in the expression and signaling pathways of JAG1 and Notch." (PMID 40026415, 2025). "We, therefore, sought to validate the interaction between Jag1 and miR-449a and the role of this interaction in modulating Notch signalling and skeletal muscle metabolism during diabetes." (PMID 31345231, 2019). "Since a previous report from our laboratory demonstrated decreased levels of miR-449a in the skeletal muscle during diabetes, we sought to evaluate the levels of its target, Jag1 in these tissues." (PMID 31345231, 2019). "In contrast, co-treatment of 10–12-week old NOD mice with OX40 L and JAG1 significantly increased functional Treg numbers and delayed the onset of diabetes." (PMID 28045060, 2017). "Tregs expanded using soluble OX40 L and JAG1 were of suppressive phenotype and delayed the onset of diabetes in NOD mice." (PMID 28045060, 2017). "Previous studies have shown that Jag1 and Dll4 are secondary to increased hyperglycemia, activate the normative and non-normative Notch1 pathways, and destroy the endothelial adhesion connection in the retina in diabetes, which is consistent with our findings." (PMID 36533134, 2022). "We also observed that Jag1 levels are elevated in the skeletal muscle of diabetic db/db mice and since miR-449a levels are inhibited in these animals, we think that such decreased miR-449a levels are responsible for increased Jag1 levels in the skeletal muscle during diabetes." (PMID 31345231, 2019). "Results suggest that miR-449a-Jag1 interaction is critical in Notch signalling and insulin signalling in the skeletal muscle and modulating this interaction might hold therapeutic potential for impaired skeletal muscle metabolism during diabetes." (PMID 31345231, 2019). "Our results indicate towards a critical role for miR-449a and its target, Jag1 in regulating Notch signalling and insulin signalling in the skeletal muscle and imply that targeting this axis might hold therapeutic potential for impaired skeletal muscle metabolism during diabetes." (PMID 31345231, 2019). "We found that the gene encoding Notch ligand delta-like 1 (DLK1) was downregulated by diabetes (p < 0.05 vs non-diabetic individuals), whereas the genes encoding delta-like 4 (DLK4) and jagged 1 (JAG1) remained unchanged." (PMID 31001672, 2019). "Intriguingly, treatment of NOD mice with either OX40 L or JAG1 alone failed to significantly alter the course of diabetes (data not shown)." (PMID 28045060, 2017).
adenoma (10 papers, 2013 to 2025). A neoplasm arising from the epithelium. "In APC-deficient adenomas, the deletion of JAG1 disrupts stem cell niche formation." (PMID 41294868, 2025). "In this study, we found the difference and the role of JAG1 in Notch signaling pathway among three lineage adenomas based on transcription data." (PMID 33425722, 2020). "Comparatively, in adenomas, ≥2-fold Notch3 expression was detected in 56% followed by Notch1 (44%), Notch4 (33%), and Notch2 (11%), while for ligand Jag1, mRNA was overexpressed in 33%, Jag2, Dll1, and Dll3 in 11%, whereas Dll4 was not expressed in adenomas." (PMID 32211044, 2020). "IF staining revealed that Jag1 and Dll4 were present at comparable levels, and localized as expected at the membrane of both normal organoids and adenoma-derived spheroids." (PMID 30065304, 2018). "We found a significant correlation between the levels of Jag1 and ICN1 in the adenoma samples (58 of 73 Jag1 high were ICN1 high; 80%, p = 0.0015) that was lost in the carcinomas." (PMID 30065304, 2018). "In particular, we isolated Jag1 WT or KO adenoma cells from ROSA26-YFP;ApcMin/+ mice and seeded under standard culture conditions for organoid and tumor/adenoma spheroids." (PMID 30065304, 2018). "We previously identified Jag1–Notch signaling as an important link between Wnt and intestinal cancer, with Jag1 as both a transcriptional target of β-catenin and a Notch signal inducer in Apc-mutant adenomas." (PMID 30065304, 2018). "To explore the mechanism by which Jag1 deletion or inhibition impacts adenoma formation, we compared the expression levels of several stem cell markers in the Jag1 KO versus WT adenomas." (PMID 30065304, 2018). "Our discovery of Jag1 dependence in ApcMin/+ adenomas raises the possibility of an alternative strategy." (PMID 30065304, 2018). "KrasG12D upregulates expressions of Notch2, Notch3, Notch4, Jag1 and downstream target genes Hes1, Hey1 and Hey2, and deletion of Jag1 partially suppresses KrasG12D-induced adenoma development." (PMID 29142904, 2017). "JAG1 appears to be the main ligand modulating the Notch-related stemness of colorectal CSCs, for instance in APC-deficient adenomas, JAG1 deletion in LGR5+ CSCs disturbs stem cell niche formation, suggesting that plasticity of these cells is highly dependent on JAG1." (PMID 37860822, 2023). "Combining miRNA-424-3p loaded nanoparticle or anti-JAG1 antibody could be an effective method for treatment strategy to PitNETs 1/2b adenomas, especially for patients with over-activation of Notch signaling and resistant to standard treatment." (PMID 33425722, 2020). "We speculated that the downstream key ligand was JAG1, instead of DLLs, in three lineage adenomas, although upstream Notch receptor was different according to histopathological type of PAs." (PMID 33425722, 2020). "The observation that adenoma initiation in the ApcMin/+ intestines required Jag1-induced Notch signaling suggested that either Jag1 was the only Notch ligand expressed in the adenomas, or adenoma-specific Notch1 was refractory to the induction by other ligands such as Dll4." (PMID 30065304, 2018). "Using mouse genetic models, therapeutic antibodies, and organoid/tumor spheroid models, we now show that epithelial Jag1 is specifically required for tumor initiation, stem cell marker expression, and stem cell activity of the adenoma cells, both in vitro and in vivo." (PMID 30065304, 2018). "Next, we exploited a potent and selective antibody antagonist targeting Jag135 to ask whether pharmacologic Jag1 inhibition would interfere with adenoma formation or growth in vivo." (PMID 30065304, 2018). "Importantly, Jag1 haploinsufficiency correlated with decreases in adenoma size and cell proliferation." (PMID 30065304, 2018).
adenoma (continued). "Interestingly, active-caspase 3 and Alcian blue stainings were both detected in cells delivered into the spheroid lumen suggesting that Notch inactivation following Jag1 deletion imposes the terminal mucosecretory differentiation of adenoma cells leading to cellular apoptosis." (PMID 30065304, 2018). "Furthermore, addiction of adenoma cells to Jag1 is mediated by MFNG." (PMID 30065304, 2018). "Together, our findings demonstrate that mouse adenomas and a particular subset of human CRC tumors require Jag1-mediated Notch signaling for effective growing and to escape from apoptosis." (PMID 30065304, 2018). "We performed immunohistochemistry (IHC) analysis of Jag1 and active ICN1 in a cohort of 135 human adenomas and 242 carcinoma samples." (PMID 30065304, 2018). "Up-regulated Notch3 and JAG1 have been observed in human non-functional PAs, but not in human pituitary glands or hormone-secreting adenomas." (PMID 33425722, 2020). "Addiction to Jag1 is concomitant with the absence of Manic Fringe (MFNG) in adenoma cells, and its ectopic expression reverts Jag1 dependence." (PMID 30065304, 2018). "In three independent experiments, we obtained 70–80 adenoma spheroids per well from 50,000 isolated YFP+ Jag1 WT cells seeded, in contrast with the Jag1 KO adenoma cells that completely failed to form spheroids." (PMID 30065304, 2018). "Together, these results indicate that Jag1 is not essential for normal intestinal homeostasis, but it is required for β-catenin-driven adenoma formation." (PMID 30065304, 2018). "In the majority of examined PA samples, an increase has been found in the expression of relative Notch3 and JAG1 mRNA, which may be a crucial factor in the initiation and proliferation of human non-functional adenomas." (PMID 33425722, 2020). "Thus, genetic deletion of epithelial Jag1 or systemic inhibition using a blocking antibody is sufficient to prevent adenoma formation in the ApcMin/+ mice, with no evident signs of toxicity." (PMID 30065304, 2018). "Supporting a role for Jag1 in adenoma formation and by extension in tumor-initiating cell (TIC) activity, Jag1 KO adenomas expressed reduced levels of Lgr5, Bmi1, Ephb2, c-Myc, Sox9, and Cd133 compared to the Jag1 WT, as determined by qRT-PCR and in situ hybridization (ISH)." (PMID 30065304, 2018).
Tetralogy of Fallot (10 papers, 2005 to 2024). A congenital cardiac malformation comprising pulmonary stenosis, overriding aorta, ventricular septum defect, and right ventricular hypertrophy. "The inactivation of Hey2, a significant Notch signaling molecule, in mice resulted in a spectrum of cardiac malformations that resembled those associated with mutations of human JAG1, associated with Tetralogy of Fallot (TOF), VSD, and tricuspid atresia." (PMID 30897084, 2019). "Recently, JAG1 has been implicated in the pathogenesis of pulmonary arterial hypertension by aggravating pulmonary vascular remodeling both in animal studies and in patients with tetralogy of Fallot and pulmonary stenosis." (PMID 31686456, 2019). "JAG1 gene (OMIM#601,920) defects result in neonatal jaundice, cardiac disease, skeletal abnormalities, ocular abnormalities and Tetralogy of Fallot." (PMID 35227291, 2022). "Mutations in NKX2-5 (5q35.1), GATA4 (8q23.1), ZFPM2 (8q23.1), GATA6 (18q11.2), GDF1 (19p13.11), JAG1 (20p12.2), and TBX1 (22q11.21) have been reported in sporadic cases with tetralogy of Fallot; however, interaction of these genes and FMR1 gene has never been reported." (PMID 28751920, 2017).
liver cancer (8 papers, 2017 to 2025). An epithelial or non-epithelial malignant neoplasm that arises from the liver. "Antibodies targeting Jag1 and Notch1 have shown remarkable potential in treating N‐Ras‐induced primary liver cancer in mice." (PMID 39113232, 2024). "Given the roles of Notch in fibrosis and liver cancer, these data suggest mesenchymal expression of Jag1 as an alternative therapeutic target." (PMID 29140985, 2017). "In addition, it has been demonstrated that inhibition of Notch2 regulated by C8orf4 could suppress the self-renewal of liver cancer stem cells(CScs) and Notch2 and Jag1 may function as novel therapeutic targets for HCC treatment." (PMID 29298665, 2018). "For cirrhosis compared with NAFLD, the most significantly upregulated genes were related to liver cancer (ITGA2, GOLM1) and inflammation (ITGA2), inflammasome activation (JAG1), and fibrosis (JAG1)." (PMID 40489530, 2025).
liver disease (8 papers, 2019 to 2024). "In our cohort, seven patients had a JAG1 mutation, one of whom was diagnosed with AS when he presented with liver dysfunction and portal hypertension." (PMID 33763395, 2021). "Interestingly, the authors found that the type of JAG1 mutation itself significantly impacted the pathogenesis of liver disease." (PMID 38398048, 2024). "Moreover, this team also modelled a disease caused by another mutation in JAG1, TOF, demonstrating that the type of JAG1 mutation has a considerable effect in the onset of liver disease." (PMID 32283585, 2020). "A second candidate genetic modifier, THROMBOSPONDIN2 (THBS2), was identified from a Genome Wide Association Study (GWAS) that stratified ALGS patients with pathogenic variants in JAG1 by whether they had mild or severe liver disease." (PMID 31343788, 2019). "Jag1 thus regulates hepatocyte injury response and thymocyte development and competence, with implications for the course of liver disease in ALGS." (PMID 39358604, 2024). "Organoids with specific mutations in the JAG1 gene showed severe liver disease and impaired development, while other organoids showed no dysfunction." (PMID 38398048, 2024). "This suggested that humans with a known JAG1 mutation and overexpression of POGLUT1 (the human homolog for Rumi) may have worse liver disease." (PMID 33172025, 2020). "When considering living related transplantation, it is important to emphasize that donors with JAG1 and/or NOTCH2 mutations should be avoided as they may have unrecognized liver disease." (PMID 33172025, 2020). "Data from the GWAS study suggested that individuals with a pathogenic JAG1 variant and increased THBS2 expression could be at risk for developing more severe liver disease." (PMID 31343788, 2019). "Our data demonstrate a multilayered role of Jag1 in the fibrotic process, affecting both hepatocyte maturation and injury response, as well as T cell differentiation and pro-fibrotic activity, providing a mechanistic framework for therapeutic modulation of Notch signaling in liver disease." (PMID 39358604, 2024).
pulmonary fibrosis (8 papers, 2016 to 2025). Chronic progressive interstitial lung disorder characterized by the replacement of the lung tissue by connective tissue, leading to progressive dyspnea, respiratory failure, or right heart failure. "Numerous studies have shown that JAG1-mediated Notch signalling is crucial for regulating human airway epithelial cell differentiation, pulmonary fibrosis and other diseases." (PMID 40999451, 2025). "CXCR7 inhibits epithelial-mesenchymal transition (EMT) and pulmonary fibrosis by blocking Jag1-Notch signaling, thereby protecting the alveolar epithelia from injury." (PMID 35111363, 2022). "Enhanced Notch signaling was discovered during pulmonary fibrosis development, while the suppression of JAG1, Notch1, NICD, and Hes-1 neutralized the development of bleomycin-induced pulmonary fibrosis." (PMID 36499287, 2022).
B-cell chronic lymphocytic leukemia (7 papers, 2012 to 2022). "Notch 1, Notch 2 and their ligands Jag1 and Jag2 are constitutively expressed in B-cell chronic lymphocytic leukemia (CLL) and confer resistance to apoptosis in malignant B-cells." (PMID 33374160, 2020). "JAG1 also induces Notch over-activation in B cell chronic lymphocytic leukemia, and JAG1 stimulation in ex vivo cultures protects from spontaneous apoptosis." (PMID 30231940, 2018). "In B-cell chronic lymphocytic leukemia (B-CLL), NOTCH1, NOTCH2, and their ligands (JAG1 and JAG2) are constitutively expressed." (PMID 35335147, 2022). "Rosati E and co-workers demonstrated a high expression of Notch 1, Notch 2, JAG1 and JAG2, in malignant B-cells isolated from 25 patients affected by B-cell chronic lymphocytic leukemia (B-CLL) but not in normal B-cells." (PMID 33374160, 2020).
melanoma (7 papers, 2011 to 2025). A malignant, usually aggressive tumor composed of atypical, neoplastic melanocytes. "For L1CAM low melanoma, a partial compensation for the lack of L1CAM could be an overexpression of JAG1 (Jagged 1), modulating Notch signaling." (PMID 29432466, 2018).
metastatic prostate carcinoma (7 papers, 2010 to 2023). A carcinoma that arises from the prostate gland and has spread to other anatomic sites. "JAG1 expression is upregulated in high-grade and metastatic prostate carcinomas and associated with poor disease-free survival of patients with PC." (PMID 36428807, 2022). "The expression levels of JAG1 and its active intracellular domain JICD are upregulated in high-grade and metastatic prostate carcinomas and associated with the poor disease-free survival of patients with PC." (PMID 36428807, 2022).
neuroblastoma (7 papers, 2014 to 2023). Neuroblastoma (NB) is the most common solid, extracranial childhood tumor. "Common genes include Jagged 1 (Jag1), Tetraspanin 2 (Tspan2), neuroblastoma, suppression of tumourigenicity 1 (Nbl1) and N-myc downstream regulated gene 2 (Ndrg2)." (PMID 25545425, 2015). "Furthermore, transduction with HES1 of several neuroblastoma cell-lines, including IMR32 and SH-SY5Y, led to inhibition of proliferation, and growth was also inhibited by treatment with recombinant Notch ligand Jag1." (PMID 32210188, 2020).
renal carcinoma (7 papers, 2015 to 2024). A carcinoma arising from the epithelium of the renal parenchyma or the renal pelvis. "Knockdown of UCA1 increased DLL1, Jag1, Jag2 and Notch1expression and decreased DLL4, NICD and Hes1 expression in renal cancer cells." (PMID 31996265, 2020). "We found knockdown of UCA1 increased DLL1, Jag1, Jag2 and Notch1expression and decreased DLL4, NICD and Hes1 expression of renal cancer cells in vivo." (PMID 31996265, 2020). "In addition, PT2385 treatment increased the expression of JAG1 in 786–0 WT cells, suggesting that combining Notch signalling inhibitors already used in clinic with PT2385 could be of benefit for renal cancer treatment." (PMID 34353313, 2021).
renal fibrosis (7 papers, 2012 to 2025). A final common manifestation of a wide variety of chronic kidney diseases characterized by glomerulosclerosis and tubulointerstitial fibrosis. "Induction of renal fibrosis has previously been demonstrated to be dependent upon Jag1/Notch1 signalling." (PMID 31570767, 2019). "Currently, only one study on transforming growth factor beta-1 (TGF-β1)-induced renal fibrosis found that LXA4 attenuated the expression of the Notch ligand Jagged1 (JAG1) and downstream molecule Hes1." (PMID 30778288, 2019).
autoimmune disease (6 papers, 2007 to 2023). A disorder resulting from loss of function or tissue destruction of an organ or multiple organs, arising from humoral or cellular immune responses of the individual to their own tissue constituents. "Hence, we focused on the JAG1 gene as a potential target for new therapies to treat autoimmune diseases." (PMID 18030350, 2007).
B cell lymphoma (6 papers, 2018 to 2023). "Studies in B cell lymphoma show that tumors stimulate the neighboring endothelium via fibroblast growth factor 4 (FGF4) to upregulate the Notch ligand Jagged 1 (JAG1)." (PMID 37887354, 2023). "Fibroblast growth factor (FGF) 4, originated from B cell lymphoma cells (LCs), was reported to activate FGFR1, which upregulated the expression of Notch ligand Jagged1 (Jag1) on neighboring ECs." (PMID 34095111, 2021).